MR1 (major histocompatibility complex, class I-related)
Diseases named in the same sentence as MR1 in open-access papers (continued):
Sharing a sentence is not in itself a finding about the gene and the disease.
Pneumocystis infection (1 paper, 2022). "In MR1−/− mice, Pneumocystis infection was cleared with kinetics similar to C57BL/6 mice." (PMID 35736127, 2022). "We used a co-housing mouse model of Pneumocystis infection, combined with flow cytometry and qPCR, to characterize the response of MAIT cells to infection in C57BL/6 mice, and, using MR1−/− mice, which lack MAIT cells, to examine their role in clearing the infection." (PMID 35736127, 2022). "While Pneumocystis infection leads to an accumulation of MAIT cells in the lung, the similar kinetics of infection and antibody responses in C57BL/6 and MR1−/− mice clearly demonstrate that MAIT cells are not needed for control of infection." (PMID 35736127, 2022).
scrub typhus (1 paper, 2016). Scrub typhus is a rare dust mite-borne infectious disease caused by the Orientia tsutsugamushi bacterium and characterized clinically by an eruptive fever which is potentially serious. "Collectively, these findings suggest that MAIT cells can be activated by IL-12 and IL-18, in an MR1-independent manner, in scrub typhus." (PMID 27463223, 2016).
staphylococcus aureus infection (1 paper, 2024). An infectious process in which the bacteria Staphylococcus aureus is present. "It has been known for a long time that Staphylococcus aureus infection exacerbates AD; and the riboflavin biosynthesis pathway of S. aureus generates MR1 antigens, which are recognized by MAIT cells." (PMID 38542456, 2024).
streptococcal infection (1 paper, 2016). Any of the several infectious disorders caused by members of streptococcus, a genus of gram positive bacteria belonging to the family Streptococcaceae. "We hypothesize that MR1-restricted T cells expressing TRAV12-2+ or other atypical TCRs selectively expand at tissue sites, such as the human mouth, tonsils and skin, associated with streptococcal infection." (PMID 27527800, 2016).
visceral leishmaniasis (1 paper, 2024). A severe form of leishmaniasis characterized by irregular bouts of fever, substantial weight loss, swelling of the spleen and liver, and anemia (which may be serious). "Nevertheless, further investigations are warranted to address extensively and precisely the roles played by MR1 and MR1-restricted cells in protozoan infections, particularly in the Visceral Leishmaniasis." (PMID 39192975, 2024).
infection (88 papers, 2010 to 2026). The state of being infected such as from the introduction of a foreign agent such as serum, vaccine, antigenic substance or organism. "Loss of Syt1 and Syt7 results in enlarged MR1 vesicles and an increased number of MR1 vesicles in close proximity to Mtb-containing vacuoles during infection." (PMID 41979188, 2026). "T cells restricted by the MR1 molecule, which includes Mucosal-associated invariant T cells (MAITs), have also been shown to play a key role during M.tb infection." (PMID 41624833, 2026). "MR1-deficient mice showed impaired ability to response to infection with E. coli or M. abscessus, and to T cell respond to infection with bovis bacillus Calmette-Guérin before the full induction of adaptive immunity." (PMID 38550591, 2024). "Mycobacteria-reactive MR1 clonotypes associate with resistance to Mycobacterium tuberculosis infection in human cohort." (PMID 38716731, 2024). "The importance of MAIT cells in mycobacterial infections is also highlighted by experiments with MR1-deficient mice that show failure to control growth of M. bovis BCG during the early stages of infection." (PMID 35164552, 2022). "We found that MAIT cell-deficient MR1−/− mice displayed similar survival times to WT mice after infection." (PMID 32811991, 2021). "Prior exposure to 5-OP-RU and CpG enhanced MAIT cell numbers in the lungs and was associated with protection against infection as reflected in a reduction in bacterial load in C57BL/6 versus MR1−/− mice." (PMID 30135490, 2018). "It will be crucial to know if such association is observed in other microbial infections in various populations, to determine if impaired MR1-antigen presentation is involved in susceptibility to infection." (PMID 29326714, 2017). "A low dose of M. bovis aerosol results in a much stronger infection in MR1-deficient mice compared with control mice, indicating the important role of MAIT cells in the early control of mycobacterial infection in the lung." (PMID 29326714, 2017). "T cell assays where MAIT cells were activated by the parental A549 and THP-1 cell lines but failed to recognize cells obtained by limiting dilution upon infection with M. smegmatis confirmed MR1 protein loss of function." (PMID 27307560, 2016). "In vitro, primary B cells and EBV-transformed B cell lines have been shown to induce MAIT cell activation in an MR1-dependent manner following infection with commensal or pathogenic intestinal bacteria." (PMID 26284072, 2015). "Infection with Cd strain 630 causes attenuated disease in mice, so we next sought to determine whether MR1-/- mice remained resistant to a more pathogenic Cd strain after an extended treatment of cefoperazone (ten days)." (PMID 31560732, 2019). "The role of MAIT cells during an infection in vivo has been demonstrated using MR1-deficient mice." (PMID 27774092, 2016). "We discuss the current understanding of MR1 immunology in M.tb infection, based on studies in both animal models and humans." (PMID 41624833, 2026). "Both WT and Mr1−/− mice were subjected to 106 CFU Salmonella Typhimurium BRD509 infection to expand the MAIT cell population followed by intratracheal bleomycin administration four weeks post-MAIT cell enrichment." (PMID 39918959, 2025). "Fragments of the detected ion at m/z 385.0994 ([M-H]-) from recombinant MR1 expressed in insect cells with M. smegmatis (mc2155) infection match the fragmentation pattern of synthetic compounds with unclear accuracy." (PMID 40746558, 2025). "In this study, we evaluated the effect of blocking CD154 with the monoclonal antibody MR1 on mouse infection with H. polygyrus." (PMID 41388224, 2025).
infection (continued). "MAIT cells accumulate in the murine lung after intranasal infection with these bacteria, and optimal activation and expansion are MR1-dependent." (PMID 40362653, 2025). "Our previous studies have revealed both modulation of MR1 antigen presentation, and direct infection of MAIT cells, therefore suggesting a direct targeting of the host MR1-MAIT cell axis by VZV for pathogenic gain." (PMID 39110717, 2024). "MR1–/– mice were shown to have comparable survival to WT mice following infection with M. tuberculosis H37Rv." (PMID 38716731, 2024). "Infection with either the Merlin or AD169 strains led to a potent reduction of total MR1 levels, consistent with the inhibition of cell surface levels as described here and previously." (PMID 36845106, 2023). "Expression of MR1 is largely localized to the ER at first, whereupon antigen loading during infection induces trafficking of MR1 to the cell surface for presentation to MAIT TCR." (PMID 36463401, 2023). "The airway epithelial cell line, BEAS-2B, is efficient at presenting Mtb to MAIT cells and the presentation of Mtb antigens by MR1 requires intracellular infection." (PMID 36430890, 2022). "In the first set of experiments, we observed activation of MR1-restricted MAIT cells for wild-type as well as recombinant strains of M. smegmatis that was dependent on the multiplicity of infection (MOI)." (PMID 35164552, 2022). "In the context of an infection, MR1 can be loaded with riboflavin metabolites or other bacterial antigens that are able to induce MAIT cell activation." (PMID 34718585, 2022). "The minor alterations in the length, flexibility and MR1–antigen contacts of the CDR3β loop consequentially drive the MAIT cell repertoire after infection, where clonal expansion occurs in those with higher functional avidity." (PMID 34718585, 2022). "MAIT cells are a subset of T cells restricted by MR1, and are able to recognize infection by a broad array of pathogens, including respiratory pathogens." (PMID 36085311, 2022). "After the pathogen infection, the DEGs of MR-1 seemed to be enriched in 117 pathways; out of which, 20 pathways were highly enriched." (PMID 35937314, 2022). "For instance, the abundance of Akkermansia was significantly increased at the later stages of infection in the riboflavin-pretreated WT and MR1–/–groups." (PMID 35722312, 2022). "Recent studies have suggested that total blood MR1-reactive T cells can stay unchanged or fall in the setting of infection or antigen-stimulation." (PMID 33479373, 2021). "We next tested the MR1 dependency of MAIT cell accumulation following infection, using a blocking anti-MR1 mAb." (PMID 34272362, 2021). "There is impaired protection against infection by pulmonary F. tularensis LVS in CD4+CD8+-depleted MR1−/− mice in contrast to their wild-type counterpart, which demonstrates MAIT cells' significance in mucosal immunity in absence of CD4+ and CD8+ T cells." (PMID 32536923, 2020). "Following infection, MR1 binds microbial ligand, and this complex is thought to traffic to the cell surface to stimulate MAIT cells." (PMID 32963314, 2020). "MAIT cell TCR-transgenic mice were better protected against infection by E. coli or M. abscessus than Mr1−/− MAIT cell TCR-transgenic mice." (PMID 32536923, 2020). "Here, the MR1 tetramer-defined MAIT cell population showed a significant decline in the CD4+ subset among total MAIT cells from pre-infection to the early chronic time point (p = 0.003; Friedman test with the Dunn’s multiple comparison test)." (PMID 31937782, 2020). "Briefly, WT, Traj33 KO and MR1 KO mice were intranasally inoculated with 105 colony-forming units of L. longbeachae and the lungs were harvested 7 days post-infection." (PMID 31113973, 2019).
infection (continued). "After a successful clearance of infection, or barrier repair, the subsequent reduction in MR1-Ag presentation would ensure this signal declined." (PMID 31533045, 2019). "In contrast to Cd630 (which exhibited 100% survival in both mouse strains), WT mice infected with CdVPI exhibited severe disease and succumbed to infection within three days, while MR1-/- mice survived the length of the experiment." (PMID 31560732, 2019). "Data from this and earlier time points indicate that C. difficile-induced IFNγ expression is mostly MR1-dependent, suggesting that the cell contact with antigen-presenting cells is essential for IFNγ responses in the acute phase of infection." (PMID 30410474, 2018). "Our data show that MAIT cells contribute to protection against fatal infection with Legionella, by a mechanism that is dependent on MR1, interferon-γ (IFN-γ) and granulocyte macrophage-colony stimulating factor (GM-CSF)." (PMID 30135490, 2018). "As an additional test for the requirement for CD4 T cell help in the generation of bone marrow IgM plasmablasts, mice were administered a CD40L-blocking antibody (MR-1), on days 8, 10, and 12 post-infection." (PMID 28575114, 2017). "To define this mechanism in the context of intracellular infection with a pathogen, we designed a screen to identify trafficking proteins that are essential for MR1-dependent MAIT cell activation in the setting of intracellular infection with Mtb." (PMID 27031111, 2016). "We have identified proteins, Stx18, VAMP4, and Rab6, which play a role in maintaining the structure of the TGN, and ultimately regulate the translocation of MR1 to the cell surface in the context of infection with Mtb." (PMID 27031111, 2016). "Further characterization of targets identified in this study will provide insight into the novel regulation of loading of ligand on MR1 and translocation of MR1 to the cell surface in the context of infection." (PMID 27031111, 2016). "In other infection model, using Mycobacterium bacillus Calmette–Guérin (BCG), MR-1 deficient mice also show higher bacterial burden in the lung compared to the WT mice." (PMID 27774092, 2016). "On the basis of our findings, we propose that non-TRAV1-2 MR1-restricted TCRs contribute to immune defence against infection primarily by providing more diverse and, in some instances, unique microbial recognition." (PMID 27527800, 2016). "Collectively, isolation of clone D462-E4 confirms the presence of microbe-reactive MR1-restricted CD8+ T cells that detect infection using an atypical MAIT TCR TRAV12-2." (PMID 27527800, 2016). "This is also evident from the increased expression levels of MR1 on lung epithelial cells following infection with MTB." (PMID 25894562, 2015). "Whereas it took wild type mice ~17 days to clear the infection, it took MR1−/− mice five additional days (~22 days)." (PMID 26217338, 2015). "The evidence for the importance of MAIT cells in controlling infection came from MR1 knockout mice, which showed a delay in clearance of the bacteria in the lungs (but not in the spleen or liver) and delayed appearance of adaptive immune responses in the lung." (PMID 26136743, 2015). "The ability to control infection with Klebsiella pneumoniae, Mycobacterium bovis bacillus Calmette–Guérin (BCG), or Francisella tularensis was found to be impaired in MR1-deficient mice." (PMID 26322041, 2015). "MR1 is ubiquitously transcribed, although cell surface expression is very low and it is only transiently upregulated following infection or incubation with some of the synthetic ligands." (PMID 26284072, 2015). "The phenotype and function of non-peptide-specific T cells will be discussed in the context of the known distribution of CD1 and MR1 molecules by different subsets of antigen-presenting cells at steady state and following infection." (PMID 26284072, 2015). "Like other innate-like cells, MAIT cells can also respond to infection in an MR1-independent manner." (PMID 26136743, 2015).
infection (continued). "The wealth of potentially antigen-selective αβ and γδ TCRs recognizing CD1- or MR1-antigen complexes hold great therapeutic potential for cancer and infection-specific T cell therapy restricted by CD1 or MR1." (PMID 26052329, 2015). "MR1−/− mice had significantly increased bacterial burden at day 10 following infection in comparison to MR1+/+ mice." (PMID 26217338, 2015). "We found a striking correlation between MR1 up-regulation and infection in the total group (p < 0.0001)." (PMID 24432025, 2014). "We demonstrate here that infection with Mtb results in a modest induction of surface expression of MR1 on epithelial cells." (PMID 20613858, 2010). "Mtb infection of A549 cells resulted in the detectable cell surface expression of MR1 while HLA-I expression was unaltered by infection with Mtb." (PMID 20613858, 2010). "Major histocompatibility complex class I-related protein 1 (MR1) presents metabolite-derived antigens to mucosal-associated invariant T (MAIT) cells and other MR1-restricted T cells, playing a critical role in immune surveillance during infection and disease." (PMID 42039519, 2026). "Additionally, we highlight recent findings on the diverse repertoire of MR1 T cell receptors that expand during infection and the current status of the MR1 ligandome." (PMID 41624833, 2026). "As in the CD4+ cell depletion experiments, we tested whether MR1 administered through the second infection period impacted the initial and/or established lung B cell populations." (PMID 38715601, 2024). "In vitro assays performed on bronchial epithelial cells infected with these recombinant strains clearly showed that intracellular infection with these metabolically loaded bacteria is successful in delivering MAIT ligands to MR1 with downstream activation of MR1-restricted MAIT cells." (PMID 35164552, 2022). "While knockdown of syntaxin 18, VAMP4 and Rab6 affected Mtb antigen presentation, only syntaxin 18 knockdown affected MR1 surface stabilization by 6-FP, suggesting distinct antigen presentation pathways between exogenously delivered antigens and an intracellular infection." (PMID 36430890, 2022). "To explore this question we compared weight loss and survival following infection in wild type mice or MR1-/- mice which have an absolute deficiency of MAIT cells, or in MR1-/- mice with a MAIT cell population reconstituted by intravenous adoptive transfer of MAIT cells." (PMID 35381137, 2021). "Consistent with this protective role of MAIT cells, Mr1−/− mice that succumbed to infection (reached humane endpoints, thus necessitating euthanasia) had significantly higher bacterial loads in the liver and spleen than matched WT mice culled at the same time points." (PMID 34272362, 2021). "This may either highlight a need for bacterial infection for optimal MR1 antigen presentation in vivo or indicate that MAIT cell expansion requires TLR-induced cytokine production at the site of infection." (PMID 32983150, 2020). "We excluded differences in infection efficiency, MR1 expression, costimulatory cytokines (IL-12), the genetic sequence of the riboflavin-encoding enzymes of S. Typhimurium, and the presence of dominant inhibitory ligands as potential mechanisms for these results." (PMID 32788367, 2020). "Interestingly, the MAIT cell clonotypes that expanded in vivo were more strongly activated in vitro in an MR1-dependent manner than those that contracted during infection, potentially due to higher functional avidity between their TCRs and MR1 ligands." (PMID 30050537, 2018). "To determine whether MAIT cells contribute to immune protection against Legionella we compared the bacterial burden in lungs of C57BL/6 and MR1−/− mice throughout infection." (PMID 30135490, 2018). "For instance, the TRAV12-2+ MR1-restricted T-cell clone can recognize infection with S. pyogenes." (PMID 27527800, 2016).